TLR2 (toll like receptor 2)
Diseases named in the same sentence as TLR2 in open-access papers (continued):
Sharing a sentence is not in itself a finding about the gene and the disease.
cancer (continued). "Examples of well-known TLR ligands that have been assessed in cancer vaccines are Pam3CSK4 and Pam2Cys for TLR-2/1 and -2/6 respectively, poly(I:C) for TLR-3, LPS and monophosphoryl lipid A (MPLA) for TLR-4, imiquimod and other imidazoquinolines for TLR-7/-8, and CpG-B for TLR-9." (PMID 32117911, 2020). "Subsequently, TACAs have been coupled with polysaccharides (zwitterionic polysaccharide, PS A1), Toll-like receptor 2 (TLR2) ligand, Pam3CysSerK4, and T-cell peptide epitopes, among others, to develop partially to fully synthetic, self-adjuvating, multi-component cancer vaccines." (PMID 31167407, 2019). "Furthermore, YAP knockdown significantly decreased HIF-1α expression and inhibited HMGB1/TLR2 induced CD133− cancer cell dedifferentiation." (PMID 31558702, 2019). "Given that TLR2 promotes the production of NO and the role of NO on the migration of cancer cells, we suspected that NO could be the connection between TLR2 and F-actin assembly." (PMID 31297109, 2019). "Thus, EGT modulates the function of TLR2 ligand in tumor macrophages, which verifies TLR2's beneficial response for cancer vaccine therapy." (PMID 31019508, 2019). "Therefore, there is a need to develop novel TLR2 agonists with higher stability in vivo, so that they are more suitable for cancer immunotherapy or for their use as immunoadjuvants." (PMID 31131189, 2019). "In the case of carcinomas, the level of TLR-2 was increased while PPARγ was decreased." (PMID 31011554, 2019). "TLR2 and A2a were co-expressed in pre-cancer and SCC cells of 17 oral specimens." (PMID 29467931, 2018). "Also, an association between TLR2 and TLR4 polymorphisms and cancer risk (particularly for gastric cancer) was shown in previous studies." (PMID 30774831, 2018). "These facts have made TLR2 agonists to be attractive adjuvants in the therapy of cancers." (PMID 28270814, 2017). "Furthermore, versican, a large extra-cellular matrix proteoglycan, enhances cancer metastasis through TLR2/6-Tpl2 mediated activation of myeloid cells in the metastatic niche." (PMID 25723737, 2015). "Nine cancers displayed high expression, and seven cancers showed low expression of TLR2." (PMID 25547486, 2014). "In term of stratified analyses by races, our findings indicated that TLR2 −196 to −174 del had an significant association with cancer risk in Caucasians and South Asians, but not in East Asians." (PMID 24376595, 2013). "All these findings suggested that polymorphisms of TLR2 and TLR4 might contribute to risk of human cancer." (PMID 24376595, 2013). "The use of systemically delivered TLR2 siRNA may thus provide a novel treatment for the prevention of cancer progression leading to better prospects of survival." (PMID 22815694, 2012). "Taken all together, although TLR2 activation by Pam2 lipopeptides is able to induce inflammatory cytokines and activate NK cells in vitro, the systemic injection of Pam2 lipopeptides as cancer adjuvants is ineffective at abolishing immune suppression." (PMID 21533081, 2011). "More immune cells expressed TLR2 in carcinoma and dysplasia than in hyperplasia (P<0.001)." (PMID 21179035, 2011). "In addition, as some bacterial vaccine and adjuvant used in cancer treatment usually contain TLR2 agonist, this study is also relevant to genetic strategy for bacterial vaccine and adjuvant design in cancer immunotherapy." (PMID 20520770, 2010). "Since common bacterial vaccine may contain TLR2 agonist, attention should also be paid to the effects of bacterial vaccines for immunotherapy on cancer cells." (PMID 20520770, 2010). "Our data indicate that cancer cells secrete Hsp70, which acts on MΦ through TLR2 to upregulate MerTK and promote M2 polarization, a previously unknown functional connection between the TLR2 and MerTK pathways." (PMID 39941817, 2025).
cancer (continued). "The interaction of TLR2 with its ligands plays a crucial role in the immune response to various pathogens, including Helicobacter pylori, a Gram-negative bacterium associated with gastric ulcers and cancer." (PMID 38732254, 2024). "Targeting TLR2 may be one of the treatment targets for cancer treatment." (PMID 38685971, 2024). "TLR signaling pathways were abundantly accumulated in Mac_C2, such as MyD88 deficiency (TLR2/4), IRAK4 deficiency (TLR2/4), regulation of TLR by endogenous ligand, and disease associated with the TLR signaling cascade, which were related to the inflammatory mechanisms of in cancers." (PMID 38918785, 2024). "Because high TLR2 expression has also been reported in other cancers and diseases, as well as our observations of fluorescently labeled TLR2-expressing metastases in this study, TLR2L-800 may potentially be used to fluorescently detect a broad range of pathologies." (PMID 39320054, 2024). "In addition, TLR2 expressed on immune cells may not only exert antitumor activity but also lead to several immune suppressive effects that indirectly promote cancer progression." (PMID 38203626, 2023). "In addition, TLR2 has been demonstrated to be involved in the regulation of immune responses in autoimmune inflammatory diseases, kidney inflammaging, tissue injuries, gut microbiome dysbiosis, diabetes and cancers." (PMID 35205112, 2022). "In addition, a study has recently revealed that endothelial TLR2 promotes angiogenesis in cancer." (PMID 35350715, 2022). "However, excessive TLR2 activation can also lead to promoting cancer progression." (PMID 35205112, 2022). "Moreover, QC-mediated anti-inflammatory and anti-apoptotic properties play a key role in cancer prevention by modulating the TLR-2 (toll-like receptor-2) and JAK-2/STAT-3 pathways and significantly inhibit STAT-3 tyrosine phosphorylation within inflammatory cells." (PMID 36233051, 2022). "Furthermore, an in vivo murine model showed a significant reduction in macrophage infiltration and inflammatory cytokine expression in TLR2 knockout mice compared to wild type (WT), revealing the necessity of TLR2 recognition of a cancer cell ligand for promotion of metastatic growth." (PMID 36389785, 2022). "However, it should be remembered that Akkermansia has also been identified as a predictor of response in patients with other cancers who received immunotherapy with PD-1 blockade, possibly through Toll-like receptor-2-dependent enhancement of antitumor immune responses." (PMID 36015331, 2022). "The extract of LarixLeptolepis (ELL) may activate TLR2 and fight cancer." (PMID 33469538, 2020). "Moreover, when expressed on cancer cells, TLR2 activation may lead to cancer cell survival, proliferation, and invasion." (PMID 33321934, 2020). "Interestingly, in follicular thyroid neoplasms, both the downregulation and upregulation of TLR4 have been connected to primary metastases and the aggressiveness of cancer, whereas TLR2 expression associated with no clinicopathological parameter." (PMID 32424768, 2020). "The role played by TLR2 in this complex interaction is ambivalent, since its ability to activate protective immune responses is counterbalanced by its immunosuppressive and pro-tumoral effects, which have prevented the diffusion of its agonists as anti-cancer drugs." (PMID 33321934, 2020). "In light of the central role exerted by TLR2 in cancer progression and in pathogen recognition, the increase of pathogens able to activate TLR2 on cancer cells and CSCs might contribute to the complex net of mechanisms underlying the pro-tumorigenic effect of particular bacteria." (PMID 33321934, 2020). "Therefore, TLR2 agonists have been used as adjuvants for anti-cancer immunotherapies." (PMID 33321934, 2020).
cancer (continued). "In addition, biglycan, through interaction with TLR2/4 receptors on the surface of macrophages, promotes inflammation by triggering the synthesis of two cytokines important for cancer progression, TNFα and CCL2, and thus enhances tumor growth in many cancer cells." (PMID 32847060, 2020). "Thus, TLR2 targeting would perfectly fits with the awareness that the future of oncology is finding the right combination of therapies that synergistically push and pull from different directions to maximize anti-cancer effectiveness." (PMID 33321934, 2020). "Thus, TLR2 agonists have been proposed as adjuvants for anti-cancer vaccination." (PMID 33321934, 2020). "Therefore, TLR2 signaling may represent a good therapeutic target to improve the efficacy of anti-cancer therapies." (PMID 33321934, 2020). "However, albeit a role for TLR2 in the promotion of cancer angiogenesis was demonstrated, we think that a comprehensive analysis of the role played by TLR2 in the complex interplay between cancer cells and the heterogeneous cell populations present in the TME is still missing." (PMID 33321934, 2020). "Recent reports indicated that TLR2, as many other TLRs, is expressed on neoplastic cells from several solid tumors, such as colon, gastric, breast, pancreatic and oral cancers, where its activation promotes cancer progression and metastasis through different cell-intrinsic mechanisms." (PMID 33321934, 2020). "Therefore, we designed this meta-analysis to explore a more accurate conclusion of whether TLR2 affects cancer risks." (PMID 31710083, 2019). "Therefore, TLR2 represents an attractive cancer immunotherapeutic target." (PMID 31131189, 2019). "Arr2, a member of the arrestin family, was proved to play a critical role in the anti-apoptotic pathway while TLR2, a member of toll-like receptors family, played an important role in innate inflammatory response, possibly affecting the progress and metastasis of cancer." (PMID 31675995, 2019). "If a similar mechanism is true in OSCC cells, TLR2 impact on carcinoma cells could be amplified." (PMID 29467931, 2018). "Recently, it has been reported that TLR2 agonists could be used directly or as structurally modified forms in cancer treatment, suggesting that TLR2 agonists can be potential effective enhancers for cancer immunotherapies." (PMID 28270814, 2017). "As TLR2 is conserved in mouse cDCs and their human counterparts, especially between murine CD8+ cDCs and the human equivalent CD141+ cDCs, agonists targeting TLR2 could be promising adjuvants in designing vaccines through activating DCs for cancer immunotherapy." (PMID 28270814, 2017). "However, continuous TLR2 expression over a long period may be a sign of cancer, as reported in cancer tissue studies." (PMID 23300722, 2012). "Interestingly, selected TLRs were downregulated in 'both' cancers, especially TLR2 and TLR3." (PMID 17280610, 2007). "eHsp90 interacts with cell-surface receptors, including low-density lipoprotein receptor-related protein-1 (LRP1) and toll-like receptors (TLR2 and TLR4), thereby promoting cancer cell proliferation, migration, and invasion." (PMID 41226319, 2025). "In this regard, the cystine/glutamate antiporter xCT, and Toll-like Receptor 2 (TLR2) represent particularly interesting candidates, having a key role in cancer progression and therapy-resistance and being (over)expressed also in OSA." (PMID 41375047, 2025). "Our previous study revealed that cancer-secreted Hsp70 exerts a marked immunosuppressive effect in TME mediated through MerTK and TLR2." (PMID 40227806, 2025). "Activation of either or both TLR2 and TLR4, and further downstream signaling via the MyD88 and NFκB pathway, has been shown in other cancerous tumors as well as mycotic keratitis." (PMID 40725140, 2025). "Previous research has demonstrated that TLR2/3 agonists induce ICD and enhance the release of DAMPs in cancer cells." (PMID 39669578, 2024).
cancer (continued). "Downstream pathways that become upregulated by TLR2 and TLR9 result in increased inflammatory signaling, which was suggested to support cancer progression over time." (PMID 38390872, 2024). "The use of a TLR2 activator (Pam2Csk8) helps to reestablish CD8+ T‐cell activity for the treatment of viral infections and cancer." (PMID 38685971, 2024). "Our findings indicate that cancer cell lines sensitive to UNE-C1 exhibit high expression of both FADD and TLR2." (PMID 39669578, 2024). "It was shown that the expression of TLR-2, TLR-4, and TLR-7 mRNA and their protein levels were significantly higher in cancer tissues compared to control tissues (p < 0.05)." (PMID 39451226, 2024). "In this context, we showed that Dectin-1, TLR2, and TLR4 are important for the basic activity of MDSCs in a fungal disease, bringing to light discoveries recently evaluated in the context of cancer and other diseases." (PMID 39035356, 2024). "While it remains unclear whether the levels of TLR2 are affected by different serum concentrations, our findings suggest that S. aureus infection in malnourished cancer patients could lead to more prominent stimulation of cancer cell proliferation than in well-nourished cancer patients." (PMID 37523113, 2024). "In this study, we utilized UNE-C1, a TLR2/6 agonist, in local mRNA therapy for tumors to demonstrate its ability to activate innate immunity and induce ICD in cancer cells." (PMID 39669578, 2024). "Based on these findings, we ultimately culminate a rational design of a liposomal apparatus integrating oridonin, maleimide, and TLR2 targeting peptide for GSH depletion and specific cancer cells delivery." (PMID 38812031, 2024). "We identified heightened expression of TLR2 as well as CLEC5A and CLEC4E in cancer samples in general and in the subgroup." (PMID 38979413, 2024). "Peptostreptococcus anaerobius activated TLR2 and TLR4 on the colon cells and increased the intracellular levels of reactive oxygen species (ROS), which promoted cholesterol synthesis and cancer cell proliferation." (PMID 37191444, 2023). "In myeloid cells, the top 50 pan-cancer central genes included seven genes involved in myeloid cell differentiation (CD4, FCER1G, IRF8, TYROBP, TLR2, TREM2 and ITGAM), but only two of them (FCER1G and TYROBP) were found among the top 50 DEGs." (PMID 36350625, 2023). "They showed that 10 Gy irradiation of cancer cell lines (U2OS, A549, HEPG2 and MCF7) increased the expression of TLR2, TLR3, TLR4, TLR6 and TLR9." (PMID 37112730, 2023). "VCAN also induced IKKβ in primary murine BMDM, which were verified by microarray to overexpress > 10-fold over cancer cells TLR1, TLR2, TLR6-9, and TLR13." (PMID 36980752, 2023). "For instance, the TLR2 natural ligand polysaccharide krestin (PSK) was able to stimulate TLR2 and elicit NK cell-mediated antitumor responses in different cancer models." (PMID 38203626, 2023). "IL-6, IL-17, TNF-α, TLR-2, and TLR-4 were significantly more highly expressed in the cancer tissues (p < 0.05)." (PMID 38075864, 2023). "Each of two pathway categories (proteoglycans in cancer and PI3K-Akt signaling) was enriched by two hub-DEGs (TLR2 and IGF2)." (PMID 35277538, 2022). "As previously reported, in the cancer-immunity cycle, CD28: (CD80, CD86), CD40, CD27, HVEM, GITR: GITRL, ICOS, and TLR-2 are stimulatory factors, while TIM-3, PD-L1: PD-1, PD-L1: (CD80, CD86), CTLA-4: (CD80, CD86), BTLA, and LAG-3 are inhibitory factors." (PMID 35419462, 2022). "TLR1, TLR2, TLR3, TLR4, and TLR5 expression levels were high across the six immune subtypes in the pan-cancer data; TLR6, TLR7, TLR8, and TLR10 expression levels were moderate; and TLR9, TLR12P, and TLR8-AS1 expression levels were extremely low." (PMID 35801728, 2022). "Thus, the TLR2 signaling pathway may be an important potential therapeutic target in cancer." (PMID 35937402, 2022).
cancer (continued). "As expected, MYC expressions in the cancer tissues were significantly upregulated, while CD247 and TLR2 were significantly downregulated in the adjacent normal tissues." (PMID 36389789, 2022). "We demonstrate that upon TLR2 stimulation, EAC cancer cells upregulate HMGB1, which translocates to the cytosol before being released extracellularly." (PMID 33922955, 2021). "The HSP70-binding A8 peptide aptamers were shown to form complexes with the exosome-expressed HSP70 and block its interaction with TLR2, thus preventing the exosome-mediated MDSC activation as well as the MDSC-conferred immune evasion of cancer cells." (PMID 34943954, 2021). "TLR2, TLR4, TLR9, and RAGE have been identified as the most common receptors for HMGB1 on cell surface in different cancer models and patients." (PMID 33614649, 2021). "Three TLR ligands are FDA-approved for cancer therapy: Bacillus Calmette-Guérin (BCG), a TLR2/4 ligand, the TLR4 ligand monophosphoryl lipid A (MPLA) and the TLR7 agonist imiquimod." (PMID 33679703, 2020). "Coley's toxin (a mixture of inactivated Streptococcus pyogenes and Serratia marcescens) and BCG (Bacillus Calmette-Guerin), a TLR2 and TLR4 agonist have been used as a drug for long-term cancer treatment." (PMID 33469538, 2020). "However, data from preclinical models suggest that TLR2 inhibition may exert anti-cancer effects." (PMID 33321934, 2020). "Knockdown of TLR2 or YAP in CD133− cancer cells decreased HIF-1α expression under normoxia condition, suggesting HIF-1α is downstream of TLR2 and YAP." (PMID 31558702, 2019). "Stressed and dying cancer cells release endogenous “danger” signals, such as ATP, S100 and HMGB1, which bind and activate the pattern recognition receptors (PRRs), frequently TLR2 or TLR4, to trigger immune responses." (PMID 30987352, 2019). "Recent approaches into the understanding of its mechanism of action showed that P-MAPA efficiently modulated TLR2 and TLR4 in both cancer and infectious diseases, besides stimulating T cells (TCD4+ and TCD8+ cells) and natural killer (NK) cell responses." (PMID 29343281, 2018). "In two separate studies, TLR2 was reported to mediate HMGB1-induced cytokine production in human embroynic kidney (HEK) cells overexpressing TLR2 and cancer stem cells." (PMID 30134807, 2018). "Because TLRs, especially TLR2 and TLR4, are implicated in the pathogenesis of OC, compounds displaying either agonist or antagonist activities may represent a potential immunotherapeutic opportunity for cancer treatment, whether used alone or in combination with other therapies." (PMID 29343281, 2018). "To determine which HMGB1 receptor(s) is involved in mediating cell invasion, we silenced four well-recognized HMGB1 receptors (RAGE, TLR2, TLR4, and CD24) individually by transiently transfecting specific shRNA oligos in Panc-1 cancer cells for 48 h." (PMID 29615080, 2018). "Activation of macrophages through their TLR2/4 leads to the release of cytokines such as IL-6 and TNF-α to adjacent cancer cells." (PMID 28969049, 2017). "Among these ligands, TLR2/4 agonist Bacillus Calmette-Guérin (BCG), TLR4 agonist monophosphoryl lipid A (MPL), and TLR7 agonist imiquimod have been approved for use in cancer therapy." (PMID 28216575, 2017). "Extract of larix leptolepis (ELL), which potentially activates TLR2 and TLR4 signaling, activates bone marrow-derived dendritic cells (BMDCs) to induce tumor-specific cytotoxic T lymphocytes (CTLs) against cancer." (PMID 28216575, 2017). "Recently, it has been shown that TLR2 and TLR4 antagonism produces an analgesic effect in behavioral tests in cancer pain models." (PMID 26962463, 2016). "In this study, we demonstrated that a Toll-like receptor 2 (TLR2) agonist-fused antigen increased antigen presentation via TLR2 signaling and induced effector memory-like CD8+ T cells against cancer after immunization." (PMID 27127171, 2016).